DEPDC1 (DEP domain containing 1)
Description:
May be involved in transcriptional regulation as a transcriptional corepressor. The DEPDC1A-ZNF224 complex may play a critical role in bladder carcinogenesis by repressing the transcription of the A20 gene, leading to transport of NF-KB protein into the nucleus, resulting in suppression of apoptosis of bladder cancer cells.
Synonyms: DEPDC1A; DEP.8; FLJ20354; SDP35; DEPDC1-V2
Tractability: PROTAC: ubiquitination databases record sites on it.
Gene: Protein-coding gene on chromosome 1 (68,474,152 to 68,497,230, reverse strand). Ensembl gene ENSG00000024526.
Subcellular location: Nucleus
Subcellular location (Human Protein Atlas): Nucleoplasm; Nucleoli fibrillar center
Gene Ontology:
Molecular function: protein binding
Biological process: negative regulation of DNA-templated transcription; intracellular signal transduction
Cellular component: fibrillar center; nucleoplasm; nucleus; transcription repressor complex
Genetic constraint (gnomAD): Loss-of-function variants: 44 observed, 60.76 expected, observed/expected ratio (o/e) 0.72, 90% interval 0.57 to 0.93. The upper end of that interval is the gene's LOEUF score, 0.93, which puts it in group 3 of 6, group 1 being the genes least tolerant of losing a copy. Missense variants: 621 observed, 742.61 expected, observed/expected ratio (o/e) 0.84, 90% interval 0.78 to 0.89. Synonymous variants: 203 observed, 252.97 expected, observed/expected ratio (o/e) 0.8, 90% interval 0.71 to 0.9.
Homologues: Orthologues: chimpanzee DEPDC1 (99% identical), macaque DEPDC1 (97% identical), dog DEPDC1 (87% identical), pig DEPDC1 (83% identical), mouse Depdc1a (82% identical), rat Depdc1 (82% identical), guinea pig DEPDC1 (57% identical), tropical clawed frog depdc1 (57% identical), zebrafish depdc1a (48% identical), Caenorhabditis elegans let-99 (14% identical). Paralogues in human: DEPDC1B (35% identical), DEPDC7 (14% identical), DEPDC4 (12% identical).
Diseases named in the same sentence as DEPDC1 in open-access papers:
DEPDC1 is named in the same sentence as 49 diseases in open-access papers, as found by Europe PMC text mining. Sharing a sentence is not in itself a finding about the gene and the disease. The quoted sentences say what the papers report.
breast cancer (30 papers, 2012 to 2025). A primary or metastatic malignant neoplasm involving the breast. "Our previous study revealed that DEPDC1 was exclusively associated with the PI3K/AKT/mTOR signaling pathway in breast cancer, and key genes involved in the activation of this pathway were enriched in patients with elevated DEPDC1 expression." (PMID 40600015, 2025). "MiR-374-5p has been shown to repress development of breast cancer through TATA-box binding protein associated factor 7 (TAF7)-mediated transcriptional regulation of DEP domain containing 1 (DEPDC1)." (PMID 35013577, 2022). "In summary, these findings showed that DEPDC1 upregulation was associated with tumor development and poorer clinical outcomes of patients with breast cancer." (PMID 31032225, 2019). "Another study also showed that DEPDC1 is associated with the antitumor activity of MELK (maternal embryonic leucine zipper kinase) inhibitor in breast cancer cells." (PMID 28969015, 2017). "Furthermore, DEPDC1 has been implicated in promoting aggressive features in breast cancer by activating the PI3K/AKT/mTOR pathway." (PMID 39068164, 2024). "Here, we examined the functional involvement and underlying mechanism of DEPDC1 in breast cancer." (PMID 31032225, 2019). "Moreover, DEPDC1 mRNA level revealed the strongest association with poor prognosis and development in breast cancer." (PMID 31032225, 2019). "In addition, we discovered that DEPDC1 caused hyper-activation of PI3K/AKT/mTOR signaling in breast cancer cells." (PMID 31032225, 2019). "Intriguingly, DEPDC1 was reported as a gene that is associated with breast cancer brain metastasis." (PMID 26918358, 2016). "While the function of DEPDC1 is unknown, its expression has been associated with poor prognosis in lung cancer and advanced disease in breast cancer." (PMID 26445238, 2015). "The percentage with high level of DEPDC1 was drastically different between normal samples and breast cancer stage I, II, III, or IV tissues (p < 0.0001), suggesting that DEPDC1 was associated with breast cancer progression and might have prognostic significance for breast cancer patients." (PMID 31032225, 2019). "Hence, these findings indicated that DEPDC1 might associate with the tumorigenesis of breast cancer." (PMID 31032225, 2019). "Recent studies have shown that DEPDC1 is overexpressed in bladder cancer, breast cancer, lung adenocarcinoma, and other malignant tumor types." (PMID 36479633, 2023). "Recent studies have shown that DEPDC1 is overexpressed in many types of malignant tumors such as bladder cancer, breast cancer, lung adenocarcinoma, and colorectal cancer." (PMID 36479633, 2023). "ZNF224 showed higher expression in bladder cancer, liver cancer and breast cancer and acted as an oncogene by recruiting DEPDC1 to form a transcription complex." (PMID 36085146, 2022). "DEPDC1 was revealed as one of the most activated genes in breast cancer by analyzing microarray data." (PMID 36072787, 2022). "DEPDC1 is a newly identified tumor-promotor gene that is abnormally expressed in many cancers and contributes to tumorigenesis, such as breast cancer, gastric cancer, and lung adenocarcinoma." (PMID 35582195, 2022). "Overexpression of DEPDC1 constantly increased the possibility of cancer development and proliferation in breast cancer cells, which was prevented by its deletion." (PMID 36072787, 2022). "Key functions and potential regulatory pathways of DEP domain-containing protein 1 (DEPDC1), a newly discovered gene related to cancer and cell cycle, have been reported in bladder cancer, and other human cancers, such as breast cancer and prostate cancer." (PMID 34556750, 2021).
breast cancer (continued). "In bladder carcinogenesis, ZNF224, interacting with the transcriptional co-repressor DEPDC1, downregulates the expression of A20, a negative regulator of the NF-kB pathway, whereas, in breast cancer, ZNF224 acts as an oncogenic transcriptional activator." (PMID 34684876, 2021). "Recent study showed that DEPDC1 was overexpressed in breast cancer tissues, with its mRNA level closely related with poor prognosis and progression of breast cancer." (PMID 33140894, 2020). "To identify the role of DEPDC1 in breast cancer, we initially explored its expression profiles between breast cancer and normal breast tissues by analyzing microarray data from GEO database." (PMID 31032225, 2019). "In summary, this section signified that the expression of DEPDC1 was positively correlated with the migration and invasion in breast cancer." (PMID 31032225, 2019). "In recent years, studies showed that DEPDC1 was also aberrantly overexpressed in lung cancer, breast cancer, hepatocellular carcinomas and prostate cancer, and had prognostic value for predicting outcomes in patients with bladder cancer and lung cancer." (PMID 31032225, 2019). "miR‐374c‐5p modulating TAF7‐regulated DEPDC1 indeed influenced the carcinogenesis and progression of breast cancer." (PMID 31162714, 2019). "And with the development of breast cancer malignancy, the expression level of DEPDC1 was increased accordingly compared primary tumor stage." (PMID 31032225, 2019). "To investigate the role of DEPDC1 in breast cancer progression, we analyzed the expression level of DEPDC1 in different stages of breast cancer patients from TCGA." (PMID 31032225, 2019). "Intriguingly, PI3K/AKT/mTOR signaling was distinctly activated in breast cancer with high DEPDC1 expression." (PMID 31032225, 2019). "In spite of DEPDC1 level was upregulated in human breast cancer tissues specimens and mouse model with ductal carcinoma in situ, less is known about its biological functions and clinical significance in breast cancer." (PMID 31032225, 2019). "In this study, the immunohistochemistry results demonstrated that DEPDC1 was high-expressed in breast cancer tissues compared with the paired adjacent normal breast tissues, and its tendency at protein level was consistent with mRNA level from TCGA data." (PMID 31032225, 2019). "Taken together, these data represented that DEPDC1 accelerated proliferation as well as movement of malignant breast cancer cells." (PMID 31032225, 2019). "To further validate the protein levels of DEPDC1 in breast cancer, we examined the DEPDC1 expression level in breast cancer tissues which were collected from Yantai Yuhuangding Hospital using immunohistochemistry." (PMID 31032225, 2019). "The data from GSE29044 showed that DEPDC1 mRNA level was significantly higher in breast cancer tissues than in normal tissues." (PMID 31032225, 2019). "Here, we drew a conclusion that miR‐374c‐5p inhibited breast cancer development via TAF7‐mediated transcriptional regulation of DEPDC1." (PMID 31162714, 2019). "GSE109169 is a publically available microarray database consisting of 25 paired breast cancer specimens, which demonstrated that DEPDC1 expression was upregulated in human breast cancer." (PMID 31032225, 2019). "The results showed that DEPDC1 mRNA and protein expression levels were dramatically enhanced in breast cancer tissues, and a step-wise increase toward tumor stage, tumor size, and distant metastasis was observed." (PMID 31032225, 2019). "In this study, we would investigate the clinical significance and functional implication of DEPDC1 in breast cancer." (PMID 31032225, 2019). "Similar to the mRNA microarray results, a raised DEPDC1 protein level was discovered in breast cancer tissues." (PMID 31032225, 2019). "All these results suggested that a positive correlation between DEPDC1 expression level and cell proliferation or cell cycle transition in breast cancer." (PMID 31032225, 2019).
breast cancer (continued). "We next assessed the biological functions of DEPDC1 in breast cancer by performing the methods of overexpression and deletion in MCF-7 and MDA-MB-231 cell lines." (PMID 31032225, 2019). "We confirmed that DEPDC1 was highly expressed in breast cancer tissues in comparison to normal tissues (2 cm adjacent from the tumor), and deletion of DEPDC1 reduced growth, migration and invasion in breast cancer cells." (PMID 31032225, 2019). "Consistently, DEPDC1 overexpression improved the growth, migration, invasion ability, and drove G1 to S phase cell cycle transition in breast cancer cells, and the deletion of DEPDC1 suppressed these malignant phenotypes." (PMID 31032225, 2019). "An increased transcript level of DEPDC1 was found in breast cancer compared with normal breast tissues." (PMID 31032225, 2019). "We further used GSEA to confirm the correlation between DEPDC1 expression level and cells proliferation in breast cancer." (PMID 31032225, 2019). "In conclusion, miR‐374c‐5p suppressed the development of breast cancer via targeting TAF7 to mediate DEPDC1, suggesting the part of miR‐374c‐5p as a latent therapeutic target for breast cancer patients." (PMID 31162714, 2019). "Further, the present study provided a novel regulatory mechanism of DEPDC1 in breast cancer by strengthening PI3K/AKT/mTOR signaling to deteriorate phenotypes." (PMID 31032225, 2019). "The CCK-8 assay showed that DEPDC1 overexpression increased the proliferation while DEPDC1 depletion inhibited the proliferation rate in breast cancer cells." (PMID 31032225, 2019). "Subsequent studies showed that DEPDC1 was also overexpressed in breast cancer, hepatocelluar carcinomas, multiple myeloma, and prostate cancer." (PMID 28969015, 2017). "It is also worthwhile to mention that DEPDC1 is located at the region of 1p31.3 that shows copy number amplification in breast cancer." (PMID 28969015, 2017). "DEPDC1 is also upregulated in several types of human cancer including breast cancer according to the public database, and a recent study indicated that DEPDC1 is related to cytoskeletal regulation." (PMID 26918358, 2016). "In addition, high expression of DEPDC1 promotes the proliferation and migration of multiple malignancies such as breast cancer, hepatocellular carcinoma, glioma, and bladder cancer, and ultimately leads to poor prognosis in patients." (PMID 36479633, 2023). "DEPDC1 is a novel cancer-related gene that was reported to be overexpressed in many tumors including bladder cancer, multiple myeloma, breast cancer, colorectal cancer, and hepatocellular carcinoma 43-47, and is known to be a poor prognostic indicator for these tumors." (PMID 33403046, 2021). "As RAS may activate PI3K, our findings might lend evidence to explain how PI3K/AKT/mTOR signalling is hyper‐activated by DEPDC1 in breast cancer cells, which was reported in a previous study." (PMID 33021072, 2020). "However, in stage I, II, III, and IV stage of breast cancer tissues, 82/177 (46%), 397/606 (66%), 150/236 (64%), and 11/15 (73%) of cases showed high expression level for DEPDC1, respectively." (PMID 31032225, 2019). "In the present study, we found DEPDC1 was highly expressed in breast cancer tissues." (PMID 31032225, 2019). "In breast cancer, DEPDC1 was one of the most upregulated genes via analyzing microarray data." (PMID 31032225, 2019). "Moreover, DEPDC1 as a novel upregulated gene, involving in proliferation, cell cycle, invasion, and metastasis in breast cancer was disclosed by GSEA from TCGA_BRCA data set." (PMID 31032225, 2019). "We uncovered that overexpressed miR‐374c‐5p inhibited the development of breast cancer via TAF7‐regulated transcriptional regulation of DEPDC1, which may be a novel and vital proportion of cancer diagnosis and treatment strategies." (PMID 31162714, 2019).
breast cancer (continued). "Moreover, to explore the mechanism of DEPDC1 correlated with cell proliferation and poor prognosis of breast cancer, we carried out gene set enrichment analysis (GSEA) for target genes of DEPDC1 in breast cancer patients." (PMID 31032225, 2019). "Finally, rescue assays represented that miR‐374c‐5p suppressed breast cancer development via TAF7‐mediated transcriptional regulation of DEPDC1." (PMID 31162714, 2019). "In this study, we explored the relationship of DEPDC1 level with NF-κB and E2F signaling pathway using GSEA, and found that these two signaling gene set were no associated with DEPDC1 level in breast cancer." (PMID 31032225, 2019). "Previously studies had indicated that DEPDC1 may act as an early molecular marker for breast cancer." (PMID 31032225, 2019). "Notably, further investigation indicated DEPDC1's ability of promoting breast cancer cells migration and invasion." (PMID 31032225, 2019). "Though further investigation is needed, our results suggest that MELK might be involved in brain metastasis of breast cancer through DEPDC1 regulation." (PMID 26918358, 2016). "Therefore, the increased DEPDC1 expression in breast cancer is correlated with disease progression and poor survival, which suggested that DEPDC1 might be a potential therapeutic target against this disease." (PMID 31032225, 2019). "We predicted that DEPDC1 could activate the signaling of PI3K/AKT/mTOR in breast cancer cells." (PMID 31032225, 2019). "However, the biological function and mechanism of DEPDC1 in breast cancer remain elusive." (PMID 31032225, 2019). "The results suggested that high DEPDC1mRNA level was significantly associated with shorter OS of breast cancer, while DEPDC1 expression level had no significantly predictive value for patients during DFS owing to breast cancer did not recrudesce in so short time." (PMID 31032225, 2019). "Multiple databases jointly certificated that DEPDC1 could be a prognostic marker for breast cancer." (PMID 31032225, 2019). "The expression levels of CCNA2, DEPDC1, and TTK (DOE-A) were significantly higher in BL/TNBCs than in luminal breast cancer cell lines." (PMID 34172056, 2021). "In recent years, several reports have also shown that DEPDC1 is aberrantly upregulated in various tumors and is involved in the occurrence and development of HCC, breast cancer, lung cancer, colorectal cancer, and glioblastoma." (PMID 34268303, 2021). "DEPDC1 has been identified in various cancers, including HCC, breast cancer, and prostate cancer, among others, and is positively involved with multiple tumorous biological processes, including proliferation, invasion etc.." (PMID 34093635, 2021). "The in vitro assays demonstrated that DEPDC1 promoted the proliferation, migration, and invasion, and involved in PI3K/AKT/mTOR signaling in breast cancer cells." (PMID 31032225, 2019). "Of these, six genes (ABAT, DEPDC1, KIF2C, SMAD4A, TAF1D, and TUBB6) have been reported to be directly relevant to cancer mechanisms, such as mammary tumor progression (P = 0.046)." (PMID 23185353, 2012). "As DEPDC1 is involved in cytoskeletal regulation and brain metastasis, MELK might be involved in brain metastasis of breast cancer via DEPDC1 regulation." (PMID 34285339, 2021). "Finally, DEPDC1 and MED28 interact with ZNF224 in bladder and breast cancer cells, respectively, and elicit two different pathways involved in the promotion and progression of tumors in two distinctive cellular milieus." (PMID 34684876, 2021). "While DEPDC1 has not been studied in meningioma, it is a known regulator of NFkB signaling and is overexpressed in multiple cancers such as glioma, breast cancer, and nasopharyngeal cancer, having been proposed as a potential therapeutic target in each." (PMID 33093491, 2020). "Further, we counted the expression of DEPDC1 in triple-negative breast cancer (TNBC) which was a highly malignant breast cancer, and observed that its expression in TNBC even higher (p < 0.0001)." (PMID 31032225, 2019).